FAM95B1 (family with sequence similarity 95 member B1)
Synonyms: PITAR; DKFZp686P0734
Gene: Transcribed unprocessed pseudogene on chromosome 9 (40,325,468 to 40,326,446, forward strand). Ensembl gene ENSG00000223839.
Diseases named in the same sentence as FAM95B1 in open-access papers:
FAM95B1 is named in the same sentence as 13 diseases in open-access papers, as found by Europe PMC text mining. Sharing a sentence is not in itself a finding about the gene and the disease. The quoted sentences say what the papers report.
glioblastoma (2 papers, 2021 to 2024). The most malignant astrocytic tumor (WHO grade IV). "FAM95B1 shows higher expression in glioblastoma (TCGA-GBM) compared with normal cortex samples from GTEx and lower-grade glioma (TCGA-LGG)." (PMID 33466745, 2021).
glioma (2 papers, 2021). A benign or malignant brain and spinal cord tumor that arises from glial cells (astrocytes, oligodendrocytes, ependymal cells). "Survival analysis using patient data from TCGA and CCGA available in GlioVis showed that FAM95B1 high expression is linked to poor glioma patient survival." (PMID 33466745, 2021). "Among these, there were six lncRNAs (TTC28-AS1, AC090425.1, GUSBP11, LINC00092, HCG18, and FAM95B1) that have not been studied in gliomas, and we visualize the Kaplan–Meier analysis results (p < 0.05)." (PMID 34615480, 2021).
lymph node metastasis (2 papers, 2020 to 2021). "Although, FAM95B1 is still a poorly characterized lncRNA, one study in papillary thyroid carcinoma showed that FAM95B1 is significantly correlated with cervical lymph node metastasis, tumor staging, and prognosis." (PMID 33466745, 2021). "For example, a bioinformatics analysis study showed that FAM95B1 and UCA1 were correlated with cervical lymph node metastasis, tumor staging, and TC prognosis." (PMID 32377223, 2020).
thyroid cancer (1 paper, 2021). "Additionally, FAM95B1 has been shown to be associated with thyroid cancer." (PMID 33499813, 2021).
cancer (2 papers, 2021 to 2024). A tumor composed of atypical neoplastic, often pleomorphic cells that invade other tissues. "(J) Relative expression (RPKM) of FAM95B1 (PITAR) across different cancer types in the TCGA Pan-cancer cohort." (PMID 39302097, 2024). "Of the three GBM and GSC-specific regulated lncRNAs, PVT1 and H19 have been extensively investigated for their role in cancer development and progression, whereas FAM95B1 (ENSG00000223839.7, NONHSAG052279.2, Lnc-ANKRD20A3-51) has not been explored for its role in cancer." (PMID 39302097, 2024).
FAM95B1 also shares sentences with these, for which no sentence is quoted: tumor (2 papers); colorectal cancer (1); endometrial cancer (1); non-small cell lung carcinoma (1); papillary thyroid carcinoma (1); prostate carcinoma (1); renal cell carcinoma (1); small cell lung carcinoma (1).